IGF2BP3 (insulin like growth factor 2 mRNA binding protein 3)
Diseases named in the same sentence as IGF2BP3 in open-access papers (continued):
Sharing a sentence is not in itself a finding about the gene and the disease.
tumor (continued). "Additionally, IGF2BP3 could accelerate the polarization of macrophage tumor-promoting phenotypes to mediate immune evasion." (PMID 37554271, 2023). "However, studies on the role of IGF2BP3 in the tumor microenvironment are scarce." (PMID 37298373, 2023). "We concluded that IGF2BP3 could serve as a candidate prognostic factor across diverse tumor types." (PMID 36761737, 2023). "Moreover, METTL3 and IGF2BP3 participated in the regulation of tumor immune surveillance." (PMID 35197058, 2022). "In addition, loss of IGF2BP3 or PDPN inhibits the expression of interleukin (IL-6) and IL-8 in OSCC cells and decreases the expression of NF-KB ligand receptor activator in OSCC xenograft tumor tissues." (PMID 36237306, 2022). "Moreover, IGF2BP3 accelerated NPC cell tumor progression and metastasis in vitro and vivo." (PMID 35136045, 2022). "Notably, the expression level of IGF2BP3 had a strong positive correlation with the infiltration scores of multiple immune cells, suggesting that different features of tumor infiltration may contribute by the expression change of IGF2BP3." (PMID 33718187, 2021). "Of note, the reduction was more evident in hypoxia condition (p = 0.005, one-way ANOVA), indicating that the impact of reduced expression of the IGF2BP3/CD164/CXCR4 oncogenic pathway may be stronger in the tumor microenvironment compared to physiological conditions." (PMID 32719743, 2020). "Moreover, the JAK/STAT inhibitor dramatically blocked the tumour‐promoting activity of IGF2BP3." (PMID 33094561, 2020). "In addition, Fu and colleagues reported that AVA 2p treatment down-regulated other two targets of the tumor suppressor miR-129-3p: IGF2BP3 (insulin like growth factor 2 mRNA binding protein 3) and CDK6 (cyclin-dependent kinase 6), both important for G1-phase progression and G1/S-transition." (PMID 31540249, 2019). "Besides, IGF2BP3 was also reported to be involved in tumor initiation." (PMID 29212181, 2017). "In addition, tumor samples would also be assessed for the presence of IGF2BP3 protein via IHC." (PMID 26244168, 2015). "Tumor expression of IGF2BP3 may hold promise as a tumor marker and/or vaccine target; however, larger studies are needed as well as determination of auto-antibody titers to IGF2BP3." (PMID 26244168, 2015). "Concurrently, immunohistochemical (IHC) analysis was conducted to assess the expression profiles of IGF2BP3, CDK6, and Ki67 across different groups of xenograft tumor tissues." (PMID 40083693, 2025). "We found more than one TA was expressed per tumor, and seven TAs (GPC3, IGF2BP3, NOL4, NR6A1, PKB, PRAME, and SPAG17) were detected in multiple tumors." (PMID 40894019, 2025). "IGF2BP3 was identified as significantly upregulated in LUAD tissues, and exhibited a positive correlation with tumor stage, T stage, and lymph node metastasis, highlighting its involvement in LUAD progression." (PMID 40801655, 2025). "The results revealed a significant positive correlation between the expression of METTL3 and IGF2BP3 and EMP1 in tumor cells." (PMID 41285728, 2025). "It exhibits strong anticancer effects through ferroptosis via IGF2BP3/GPX4 pathways, induces mitochondrial apoptosis, and targets NF-κB, ERK, and PI3K/Akt/mTOR to suppress tumor progression." (PMID 41465430, 2025). "High co-expression of IGF2BP3 and OLFML1 was significantly correlated with larger tumor size and advanced T stage." (PMID 40765816, 2025). "In xenograft models, silencing RBM15, IGF2BP3, or YTHDF2 significantly reduces VEGFA expression and suppresses tumor growth." (PMID 41403702, 2025). "Colony formation assays and tumor sphere formation assays revealed that OLFML1 knockdown significantly reduced the colony-forming ability and stemness promoted by IGF2BP3 overexpression." (PMID 40765816, 2025). "Most regulators, such as METTL3, YTHDF1, IGF2BP3, and RBMX, were upregulated in tumor tissues, while METTL14 and ZC3H13 were downregulated." (PMID 40916616, 2025).
tumor (continued). "Clinical analyses further reveal a positive correlation between VEGFA expression and RBM15/IGF2BP3/YTHDF2 levels, underscoring the central role of RBM15-mediated m6A modification in VEGFA regulation and tumor angiogenesis." (PMID 41403702, 2025). "IGF2BP3 is preferentially expressed in TNBC, where it is significantly more abundant in tumor-initiating BC cells and promotes EMT and stem-like properties." (PMID 38600165, 2024). "The methylation of HDGF mRNA mediated by METTL3 enhances mRNA stability and was directly recognized by the m6A reader IGF2BP3 that bound to the m6A site of HDGF mRNA, which facilitates subsequent tumor growth and liver metastasis in GC." (PMID 39009956, 2024). "The interaction between IGF2BP3, TRIM25, and miR-3614 delineated a novel regulatory pathway crucial for tumor cell proliferation." (PMID 38338932, 2024). "IHC results showed that IGF2BP3 knockdown led to a lower level of NFAT1 and higher level of IRF1 in xenograft tumor tissues." (PMID 38448411, 2024). "Inhibition of IGF2BP3-induced expression of IRF1 activates interferon (IFN) signaling pathway and then exerts its anti-tumor effect." (PMID 38448411, 2024). "Mechanically, we revealed that WTAP and IGF2BP3 regulated GBE1 expression via m6A modification and also demonstrated that GBE1 facilitates PC cell proliferation, stemness-like properties and tumor growth." (PMID 38961325, 2024). "Among that, the protein expression of IGF2BP3, B2M, CD36, CDKN1A, ANKRD33B, and LHFPL2 were up-regulated; However, the protein expression of APP and CTDSPL was low in both normal and tumor tissues." (PMID 39470474, 2024). "We come to a conclusion that the proposed modulatory model of IGF2BP3 in CC, in which IGF2BP3 regulates the methylation of SCD mRNA by IGF2BP3-METTL14 complex, thereby accelerating lipid metabolism and tumor progression in CC." (PMID 38355626, 2024). "As a result, in CRC, METTL3, METTL14, WTAP, IGF2BP3, YTHDC1, and FTO orchestrate tumor angiogenesis through diverse pathways and mechanisms, thereby affecting the initiation, progression, and prognosis of CRC." (PMID 39295872, 2024). "IGF2BP1 expression was low in both normal esophageal tissue and tumor tissue, while IGF2BP2 and IGF2BP3 expression was higher in tumor tissue than in normal esophageal tissue." (PMID 38724996, 2024). "Lastly, the IGF2BP3 knockdown restrained CC growth and lipid metabolism, after which SCD overexpression rescued the influence in vitro and in vivo using nude mouse tumor-bearing model." (PMID 38355626, 2024). "Among them, the RNA-binding protein IGF2BP3, which sustains the translation of IGF1R in the cytoplasm of tumor cells, was encapsulated in extracellular vesicles extracted from Ewing sarcoma cell lines." (PMID 38892104, 2024). "Research has shown that m6A readers such as IGF2BP2, IGF2BP3, YTHDF2, and YTHDF3 are involved in tumor angiogenesis, further influencing the occurrence and development of tumors and potentially affecting the prognosis of patients with tumors to some extent." (PMID 39295872, 2024). "Taken together, these data indicate that RNA decoy oligonucleotides, specifically bound to IGF2BP3, reduce the cancer‐related splicing events of PIP4K2A and inhibit tumor growth and metastasis." (PMID 38059827, 2024). "repressing IGF2BP3/c‐MYC/LOC101929709/LIN28B/PI3K–AKT pathway inhibited the Warburg effect and tumor progression." (PMID 38721006, 2024). "IGF2BP3 regulates the stability and translation of NFAT1 mRNA in a m6A-dependent manner, and NFAT1 negatively mediates tumor suppressor IRF1 expression through regulating its transcription." (PMID 38448411, 2024). "Evidence has shown that IGF2BP3 inhibits the activation of CD8+ T cells and facilitates tumor immune evasion." (PMID 38902779, 2024). "Strikingly, the transcriptional regulation of IGF2BP3 by ZBTB48 leads to the formation of a positive feedback loop that continuously activates and strengthens the tumor-initiating potential of GSCs." (PMID 37723588, 2023).
tumor (continued). "IGF2BP3 is an RBP and can affect tumor progression by targeting mRNA for MMP1, CD44, CDK164, ABCG2, IGF2 and other genes." (PMID 37340423, 2023). "In summary, we here show that IGF2BP3 facilitates NOTCH3 mRNA stability to promote Notch3 signaling activation, then enhances the survival and tumor-initiating activity in disseminated tumor cells, leading to robust tumor metastasis in NPC." (PMID 37853162, 2023). "Mechanistically, IGF2BP3 activates Notch3 signaling by maintaining NOTCH3 mRNA stability in an m6A-dependent manner, thus enhancing the tumor-initiating ability of DTCs and promoting the development of metastasis." (PMID 37853162, 2023). "IGF2BP3 and N3ICD levels were potently upregulated in NPC primary tumor samples from the patients with metastatic NPC compared to those without metastasis, suggesting the significant relevance of the IGF2BP3/Notch3 axis in NPC." (PMID 37853162, 2023). "The upregulation of hsa_circ_0003258 promotes tumour formation via the hsa_circ_0003258/miR 653p/ARHGAP5 axis, as well as the hsa_circ_0003258/IGF2BP3/HDAC4 axis, according to a recent study." (PMID 36840946, 2023). "Usually, IGF2BP3 is an RBP and has been shown to affect tumor progression by binding to mRNA and affecting mRNA cleavage, translation and stability." (PMID 37340423, 2023). "IGF2BP3 shares 73% amino acid sequence identity with IGF2BP1 and is particularly interesting in tumorigenesis and tumor progression." (PMID 37426488, 2023). "IGF2BP3 regulates the cell cycle and angiogenesis by targeting CCND1 mRNA and VEGF mRNA via reading m6A modifications, thus promoting tumor growth in vivo." (PMID 37298373, 2023). "Consistently, IGF2BP3 overexpression increased the tumor initiating cell (TIC) frequency, whereas IGF2BP3 silencing had the reverse effect." (PMID 37853162, 2023). "For patients with both primary and recurrent tumor samples included in the TMA, IGF2BP3 positivity appeared to increase after recurrence (p = 0.03), with a clear positive trend in subsequent recurrences." (PMID 37760460, 2023). "In a previous study, IGF2BP3 was reported to be regulated by the E3 ubiquitin ligase MKRN2, which is also a tumour suppressor." (PMID 37877353, 2023). "We compared the expression levels of IGF2BP3, P4HB, RAC3 and CLK2 in TCGA BCa tissues and normal tissues, and the results showed that all four genes were significantly upregulated in tumor tissues." (PMID 38299148, 2023). "IGF2BP3 exerted its function via the regulation of TMB, MSI, tumor immune microenvironment (TME), and drug sensitivity." (PMID 36761737, 2023). "Distinguishingly, IGF2BP2 is ubiquitously expressed in normal adult and tumor tissues, whereas IGF2BP1 and IGF2BP3 are de novo synthesized during numerous malignancies, earning themselves the label of bona fide oncofetal proteins." (PMID 37554271, 2023). "IGF2BP3 which bind Lnc-DMDRMR to stabilize the cell-cycle kinase CDK4 in an m6A-dependent manner, ultimately enhancing the G1-S transition and promoting tumour progression in RCC." (PMID 37284313, 2023). "Abundance analyses revealed that the expression of IGF2BP3 was higher in AXT cells than in AX cells, which show less malignancy than the former, and contributed to activating tumors and promoting tumor cell growth in vivo and in vitro." (PMID 37426488, 2023). "Insulin-like growth factor 2 mRNA-binding protein 3 (IGF2BP3) plays a key role in tumorigenesis and tumor progression." (PMID 35845940, 2022). "Yellow background indicated the most significant (p < 0.0001) genes up-regulated in tumor tissues, including HNRNPC, YTHDF1, IGF2BP1, YTHDF2, RBM15, and IGF2BP3." (PMID 35581263, 2022). "IGF2BP3, which belongs to a conserved IGF2 mRNA-binding protein family, was highly expressed in several tumor types including lung cancer, colon cancer, melanoma and cell carcinoma." (PMID 36401176, 2022). "Western blotting analysis revealed significantly increased IGF2BP3, p-PI3K, p-AKT and BCL2 expression in AB+-treated tumor tissues." (PMID 35615150, 2022).
tumor (continued). "Meanwhile, compared with IGF2BP1 and IGF2BP3, IGF2BP2 expression exhibited striking intra- and inter-tumor heterogeneity." (PMID 36686749, 2022). "Upregulation of hsa_circ_0003258 drives tumor progression through both hsa_circ_0003258/miR-653-5p/ARHGAP5 axis and hsa_circ_0003258/IGF2BP3 /HDAC4 axis." (PMID 34986849, 2022). "Combined inhibition of IGF2BP3 and HIF-1α is reported to further prevent tumor angiogenesis and metastasis." (PMID 35794625, 2022). "B-NDG and BALB/c mice were used to construct xenograft tumor models to verify the phenotypes upon METTL3 and IGF2BP3 silencing." (PMID 35197058, 2022). "IGF2BP3 expression was higher in most of the tumor tissues (n = 30/34) and lower in PRAD (P < 0.05); IGF2BP3 expression in READ (P > 0.05), TGCT (P > 0.05), and PCPG (P > 0.05) tumors was similar to that of normal tissues." (PMID 36686749, 2022). "Next, we measured the mRNA levels of KLK5 in the tumor and peritumoral tissues of human GBC, and investigated the relationship between IGF2BP3 and KLK5 from a clinical perspective." (PMID 36313631, 2022). "Overexpression of IGF2BP3 upregulates HIF-α in gastric cancer and promotes hypoxia-induced angiogenesis and tumor invasion." (PMID 35794625, 2022). "Consistent with the transcriptome data, the protein expression of 4 genes (IGF2BP1, IGF2BP3, HMMR and ADAMTS12) were up-regulated in LUAD tumor samples." (PMID 34721973, 2021). "The IGF2BP3 and HNRNPC expression in different subtypes of the stage, molecular, and immunity was analyzed using an integrated repository portal for tumor-immune system interactions (TISIDB)." (PMID 33796449, 2021). "This is the first study to elucidate the biological functions of the IGF2BP3/HIF1A axis in hypoxia-induced adaptive responses and hypoxia-triggered tumor malignant progression in SC." (PMID 34621671, 2021). "We demonstrated that high IGF2BP3 mRNA expression levels correlated with EWS metastasis and disease progression in well-characterized EWS tumor specimens." (PMID 32719743, 2020). "This study provides novel evidence that gC1qR can suppress the tumor-inhibiting role of C1q and regulate CKS1B mRNA through IGF2BP3 in MM patients with Amp1q21." (PMID 32760394, 2020). "However, considering that CXCR4 may be up-regulated by epigenetic alterations or hypoxia-driven signaling which allow tumor cells to adapt and win the selection leading to tumor cell dissemination and metastasis in a new host environment, inhibition of IGF2BP3 may be more relevant." (PMID 32719743, 2020). "IGF2BP3 is upregulated in tumor-initiating CD133+CD49f+ cells in mouse HCC and promotes their pluripotency and tumorigenesis by inhibiting TGF-β tumor suppressor pathway." (PMID 29736175, 2018). "IGF2BP3 is upregulated by EGFR, which promotes tumor cell migration and invasion by inducing expression of pre-migration/invasion genes." (PMID 29088808, 2017). "Other IGF family members with increased RNA message levels in this tumor (compared to muscle and bone) include IGFBPL1 (5-6-log2-fold), IGFL3 (6-7-log2-fold), and IGF2BP3 (2-6-log2-fold)." (PMID 25861239, 2015). "Silencing IGF2BP3, a TLR4/NANOG–dependent gene, inhibits pluripotency genes and tumorigenesis and abrogates the chemoresistance of tumor-initiating cells." (PMID 26327240, 2015). "A total of 84 paired tumor and normal tissue specimens were assessed from patients with Stage 2 and 3 CRC; 43% of tumors had IGF2BP3 mRNA expression levels greater than 0.1 % of that of testis and were considered positive." (PMID 26244168, 2015). "IGF2BP3 overexpression enriched the CD133+ CSC subpopulation in HCC, enhanced tumor sphere formation and suppressed the cytotoxic effects of sorafenib and doxorubicin." (PMID 26327240, 2015). "The expression of IGF2BP3 was significantly and positively correlated with that of IGF-2 in tumor cells (P = 0.02)." (PMID 20178612, 2010).
tumor (continued). "(iv) Insulin-like growth factor 2 mRNA binding protein 3 (IGF2BP3), is found in the nucleolus, is over-expressed in human tumours and represses IGF2 during late development." (PMID 18416826, 2008). "Additionally, IGF2BP2 is widely expressed in both normal and tumor tissues, while IGF2BP1 and IGF2BP3 are overexpressed in many malignant tumors and are considered oncofetal proteins." (PMID 40088376, 2025). "Given that IGF2BP3 is known to influence this microenvironment, we are analyzing prognostic models’ impact on KIRC immunity to assess the roles of IGF2BP3, CENPA, and MEF2B axis as a whole factor in tumor immunity." (PMID 41589308, 2025). "Although reliable early detection biomarkers are still lacking, our study contributes by identifying IGF2BP3 as a potential prognostic biomarker and a key player in tumor progression." (PMID 40162116, 2025). "Combining the results of the PPI network and correlation analysis, we inferred that IGF2BP3 may regulate CENPA protein levels, which in turn affects the transcription of downstream target genes and functions as a regulator of tumor progression." (PMID 41589308, 2025). "Furthermore, high MCMBP expression correlates with elevated levels of m6A “readers” (IGF2BP1, IGF2BP3) and “writers” (VIRMA, YTHDF3), a state thought to promote tumor progression by enhancing the stability and translation of oncogenic mRNAs." (PMID 41346611, 2025). "Similarly, in colon cancer, IGF2BP3 has been identified as a regulator of vascular endothelial growth factor (VEGF) mRNA stability via m6A modification, facilitating tumor angiogenesis." (PMID 40356596, 2025). "Meanwhile, after cisplatin administration, the tumor volume and weight of nude mice in the IGF2BP3 overexpression group were not significantly reduced compared with the saline group, indicating the sensitivity of cisplatin chemotherapy inhibited by IGF2BP3." (PMID 40083693, 2025). "Together, our findings indicate that IGF2BP3 is not crucial for cell viability but is important for MCC tumor progression." (PMID 40162116, 2025). "IGF2BP3, as the m6A reader, directly recognized and bound with the m6A site of HDGF mRNA stability mediated by elevated METTL3 expression, which are correlated with tumor angiogenesis and liver metastasis by maintaining HDGF mRNA stability." (PMID 39009956, 2024). "IGF2BP3 and HIF-1α together affect cancer cell metastasis and neovascularization, while inhibiting their expression better inhibits adverse factors that accelerate tumor progression." (PMID 39033180, 2024). "Overall, our results demonstrate that lncRNA ZNF674-AS1, which significantly up-regulated in chemotherapy non-response NB patients, plays a crucial role in promoting NB tumor development and inhibiting cisplatin-induced tumor cell pyroptosis through up-regulating CA9 by binding IGF2BP3." (PMID 38177154, 2024). "Further research data suggest that IGF2BP3 inhibits the expression of VEGF by reading and promoting the decay of m6A-modified mRNAs, thereby suppressing angiogenesis in CC tumor cells and inhibiting tumor growth." (PMID 39295872, 2024). "Therefore, it came to the conclusion that IGF2BP3 activated the HMGB1 related pathways and participated in tumor progression of BLCA." (PMID 38504159, 2024). "Moreover, mechanism studies revealed that ZNF674-AS1 interacted with IGF2BP3 to regulate the transcriptional level of Carbonic Anhydrase IX (CA9), a key enzyme involved in tumor growth and correlated with the clinical prognosis of NB patients." (PMID 38177154, 2024). "Vikesaa compared the phenotypes of IGF2BP3‐silenced cells and nonsilenced cells in vitro and observed that tumour cells expressing IGF2BP3 showed significant cell elongation and motility phenotypes, such as increased adhesion between cells." (PMID 38358034, 2024). "IGF2BP3, as a RBP, may enhance cancer-derived cellular growth and migratory ability in tumor progression." (PMID 38355626, 2024).